BRWD1 (bromodomain and WD repeat domain containing 1)
Description:
May be a transcriptional activator. May be involved in chromatin remodeling (By similarity). Required for regulation of cell morphology and cytoskeletal organization.
Synonyms: C21orf107; WDR9; FLJ11315; N143; DCAF19; CILD51; WRD9
Tractability: Small molecule: a high-quality ligand is known. Antibody: its Gene Ontology location is reachable by antibodies, with medium confidence. PROTAC: ubiquitination databases record sites on it; a small molecule that binds it is known.
Target class: Epigenetic regulator; Bromodomain; Reader
Gene: Protein-coding gene on chromosome 21 (39,184,176 to 39,321,559, reverse strand). Ensembl gene ENSG00000185658.
Subcellular location: Cytoplasm; Nucleus; Cell projection, cilium membrane; Cytoplasm, cytoskeleton, flagellum axoneme
Subcellular location (Human Protein Atlas): Cytosol; Nucleoplasm; Mitotic spindle; Nucleoli; Plasma membrane; Vesicles
Pathways (Reactome):
Chromatin organization: Chromatin modifying enzymes
Immune System: Interleukin-7 signaling
Gene Ontology:
Biological process: cytoskeleton organization; regulation of cell shape; regulation of transcription by RNA polymerase II
Cellular component: axoneme; motile cilium; nucleolus; nucleoplasm; nucleus; cytoplasm; ciliary membrane
Genetic constraint (gnomAD): Loss-of-function variants: 74 observed, 201 expected, observed/expected ratio (o/e) 0.37, 90% interval 0.3 to 0.45. The upper end of that interval is the gene's LOEUF score, 0.45, which puts it in group 1 of 6, group 1 being the genes least tolerant of losing a copy. Missense variants: 2,041 observed, 2,502.5 expected, observed/expected ratio (o/e) 0.82, 90% interval 0.79 to 0.85. Synonymous variants: 843 observed, 851.57 expected, observed/expected ratio (o/e) 0.99, 90% interval 0.94 to 1.05.
Gene-disease validity (ClinGen):
ClinGen rates the evidence that BRWD1 causes each of these diseases.
agammaglobulinemia (autosomal dominant): Limited. A decreased level of serum immunoglobulins.
primary ciliary dyskinesia (autosomal recessive): Disputed. A rare, genetically heterogeneous, primarily respiratory disorder characterized by chronic upper and lower respiratory tract disease.
Homologues: Orthologues: chimpanzee BRWD1 (97% identical), macaque BRWD1 (95% identical), dog BRWD1 (86% identical), rabbit BRWD1 (85% identical), pig BRWD1 (84% identical), rat Brwd1 (78% identical), mouse Brwd1 (78% identical), zebrafish brwd1 (42% identical), tropical clawed frog brwd1 (41% identical), Drosophila melanogaster BRWD3 (31% identical). Paralogues in human: BRWD3 (43% identical), PHIP (42% identical).
Diseases named in the same sentence as BRWD1 in open-access papers:
BRWD1 is named in the same sentence as 19 diseases in open-access papers, as found by Europe PMC text mining. Sharing a sentence is not in itself a finding about the gene and the disease. The quoted sentences say what the papers report.
Down syndrome (3 papers, 2022 to 2025). "Here, we found that the HSA21-encoded chromatin effector, BRWD1, was upregulated in neurons derived from iPS cells from an individual with Down syndrome and brain of trisomic mice." (PMID 36289231, 2022). "Similarly, NMDA-dependent LTP can be rescued either by the copy number restauration of Dyrk1a levels or Brwd1 in the Ts65Dn mouse model of Down syndrome." (PMID 40003558, 2025). "This approach could be useful for the treatment of a multitude of brain disorders that result from the overexpression of epigenetic regulators (such as BRWD1 in Down syndrome), or when there is a global imbalance of histone PTMs due to LoF mutations." (PMID 40160416, 2025).
Infertility (2 papers, 2024 to 2025). "Such a phenotype has been observed in KPNA6 KO mice, where the translocation of the transcription factor BRWD1 and the expression of transition nuclear proteins and protamines was markedly reduced, which resulted in a total infertility and reduced sperm count < 3% compared to WT." (PMID 39423201, 2024).
osteoarthritis (2 papers, 2021). A noninflammatory degenerative joint disease occurring chiefly in older persons, characterized by degeneration of the articular cartilage, hypertrophy of bone at the margins and changes in the synovial membrane. "Such as has_circ_0136474, which regulates IL-1β-Induced chondrocyte injury through miR-766-3p/DNMT3A Signaling Pathway; Circ-BRWD1, which contributes to osteoarthritis development through the modulation of miR-1277/TRAF6 axis." (PMID 34652255, 2021).
B cell deficiency (1 paper, 2018). A broad classification of disorders where circulating numbers of B lymphocytes are decreased or ineffective. "This could explain why the B-cell deficiency observed in some patients was more severe than that observed in Brwd1-/- mice." (PMID 30250168, 2018).
breast carcinoma (1 paper, 2013). "Evaluation of bRWD1 versus a similarly biotinylated fully human IgG1κ MAb, which recognizes a hapten not present in mammalian tissues, on a human breast cancer tissue microarray demonstrated expression of RYK on stroma and cancer cells in tumor cores." (PMID 24058687, 2013).
cervical cancer (1 paper, 2025). A primary or metastatic malignant neoplasm involving the cervix.
cognitive deficits (1 paper, 2022). "We then investigated whether acute Brwd1 overexpression in euploid animals may be sufficient to cause DS-related cognitive deficits." (PMID 36289231, 2022). "In conclusion, we demonstrated that a previously uncharacterized binder of the BAF complex, BRWD1, is critically involved in regulating aberrant neuronal gene expression patterns in DS-like brain, which precipitate synaptic and cognitive deficits associated with this disorder." (PMID 36289231, 2022). "Together with our previous results, these data demonstrate that Brwd1 upregulation in DS-like brain is both necessary and sufficient to promote synaptic and cognitive deficits associated with the disorder, and that Brwd1 copy number restoration fully rescues these effects in male mice." (PMID 36289231, 2022). "Selective restoration of Brwd1 copy number in trisomic mice rescued DS-related cognitive impairments, neuronal physiology, and alterations in transcription." (PMID 36289231, 2022). "Furthermore, Brwd1 copy number restoration did not significantly rescue these cognitive deficits, reflecting a more limited contribution of Brwd1 to Ts65Dn hippocampal function in females." (PMID 36289231, 2022).
female infertility (1 paper, 2019). Diminished or absent ability of a female to achieve conception. "By searching MPD, we found that mutations in BRWD1 of mouse may cause female infertility." (PMID 30935378, 2019).
male infertility (1 paper, 2021). The inability of the male to effect fertilization of an ovum after a specified period of unprotected intercourse. "Although a distinct pathway has not been found yet, the reduced transcription of postmeiotic genes, including Tnp1, Tnp2, Prm1 and Prm2, in Brwd1-defective testes has been suggested to cause male infertility." (PMID 34473250, 2021).
microcephaly (1 paper, 2025). A congenital or acquired developmental disorder in which the circumference of the head is smaller than normal for the person's age and sex. "Duplication involving PSMG1 and BRWD1 (Case 10) implicates disruptions in proteasome biogenesis and chromatin remodeling in patients with severe morphological anomalies and microcephaly." (PMID 40869915, 2025).
hematological malignancies (1 paper, 2025). "Though the function of BRWD3 in hematological malignancies has not been revealed yet, BRWD1 is considered as a master orchestrator of late B-cell development." (PMID 40282457, 2025).
BRWD1 also shares sentences with these, for which no sentence is quoted: bipolar disorder (2 papers); tumor (2); acute kidney injury (1); Alzheimer disease (1); Anxiety (1); cancer (1); hyperthymia (1); malignant lymphoma (1).